PLD2 (phospholipase D2)
Diseases named in the same sentence as PLD2 in open-access papers (continued):
Sharing a sentence is not in itself a finding about the gene and the disease.
ischemic stroke (3 papers, 2016 to 2020). A stroke disorder caused by obstruction of blood flow to the brain, due to thrombotic (local blood clot formation) or embolic (due to a blood clot or other material traveling from another site) event. "Previous studies indicate that of deletion of Pld1 and Pld2 protects against development of arterial thrombosis and ischemic stroke." (PMID 27299737, 2016). "Here, we confirmed that PLD1 might play more important roles than PLD2 and that both PLD1 and PLD2 act synergistically, or partially redundantly, in regulating thrombosis-relevant events, including acute pulmonary thrombosis and ischemic stroke, in mice." (PMID 32971863, 2020). "Treatment of platelets and mice with the PLD inhibitor FIPI (5-Fluoro-2-Indolyl Deschlorohalopemide) known to inhibit the enzymatic activity of both PLD1 and PLD2 resulted in altered platelet activation and protection against FeCl3 injury and ischemic stroke as observed in Pld1-/-/Pld2-/-mice." (PMID 30555342, 2018). "However, deletion of PLD1 and PLD2 in mice is protective against arterial thrombosis and ischemic stroke." (PMID 27299737, 2016). "Therefore, in the present study, we further used two different thrombotic models of acute pulmonary thrombosis and ischemic stroke, to define the roles of PLD1 and PLD2." (PMID 32971863, 2020). "Likewise, only PLD1 inhibition, but not PLD2 inhibition, could partially improve ischemic stroke, and inhibition of both PLD1 and PLD2 could afford considerable protection against ischemic stroke." (PMID 32971863, 2020).
melanoma (3 papers, 2017 to 2025). A malignant, usually aggressive tumor composed of atypical, neoplastic melanocytes. "TUNEL assay revealed less apoptotic cells in B16 melanoma tumors formed in Pld2−/− mice." (PMID 29674728, 2018). "When B16 melanoma cells stably expressing the fluorescent protein mCherry were implanted, apoptosis of these cells in the tumor formed in Pld2−/− mice was significantly suppressed, which was consistent with the result of immunostaining of cleaved caspase 3, a specific marker for apoptotic cells." (PMID 29674728, 2018). "Consistent with the result with Pld2−/− mice, growth of the tumor produced by B16 melanoma cells in Pld2−/− mice grafted with Pld2−/− bone marrow cells (rKOdKO) was significantly enhanced compared with that in WT mice grafted with control bone marrow cells (rWTdWT)." (PMID 29674728, 2018). "Thus in melanoma, loss of LKB1 in PLD2 overexpressing tumours may further contribute to mTOR activation, whereas in benign neoplasia higher LKB1 level counterbalance aberrant PLD2 activation." (PMID 28649994, 2017). "Furthermore, downregulation of LKB1 in malignant melanoma specimen, which exhibit activated Akt and overexpression of PLD2, correlates with enhanced mTOR activity, indicating that the mechanism described in this study contributes to pathogenesis of malignant melanoma." (PMID 28649994, 2017). "Consistent with the result obtained with Pld2−/− mice, Pld2−/−/Cas9 mice implanted with B16 melanoma and LLC cells enhanced tumor growth, confirming that ablation of Pld2 promotes the tumor growth." (PMID 29674728, 2018).
prostate carcinoma (3 papers, 2014 to 2022). A carcinoma that arises from epithelial cells of the prostate gland. "Surprisingly, the role of PLD1 and PLD2 in prostate cancer (PCa), the commonest cancer of men in the western world, has not been widely investigated." (PMID 31673104, 2019). "Here a role for PLD2 in prostate cancer (PCa), the major cancer of men in the western world, is examined." (PMID 31673104, 2019). "Because osteosclerotic behavior is a feature of the bone metastatic niche, it was proposed that targeting PLD2 could prevent or retard bone metastasis of prostate cancer." (PMID 36320056, 2022). "Halopemide is a non-specific PLD2 inhibitor that can reduce prostate cancer cell-derived exosome secretion and incapacitate these exosomes to stimulate the proliferation and mineralization of osteoblasts." (PMID 36320056, 2022).
psoriasis (3 papers, 2017 to 2022). An autoimmune condition characterized by red, well-delineated plaques with silvery scales that are usually on the extensor surfaces and scalp. "Based on the results obtained with oral glycerol in wild-type mice versus PLD2 knockout mice, we sought to further characterize the effects of oral glycerol on other markers of psoriasis in wild-type mice." (PMID 34445455, 2021). "Here, we hypothesized that glycerol, as the precursor of phosphatidylglycerol, would inhibit keratinocyte proliferation and psoriasiform lesion development in the IMQ mouse model of psoriasis and that PLD2 would be required for this beneficial effect of glycerol." (PMID 34445455, 2021). "Notably, the PLD2/AQP3 signaling module was observed to be abnormal in psoriasis and non-melanoma skin cancers, suggesting a possible involvement of dysregulation of this module in such hyperproliferative skin diseases." (PMID 32528559, 2017).
renal carcinoma (3 papers, 2019 to 2024). A carcinoma arising from the epithelium of the renal parenchyma or the renal pelvis. "Furthermore, pharmacological inhibition of PLD2 was sufficient to suppress tumour growth and dissemination while PLD2 has also been shown to regulate the expression of HIF1α in renal cancer cells." (PMID 31922096, 2019).
acute myocardial infarction (2 papers, 2020). Necrosis of the myocardium, as a result of interruption of the blood supply to the area. "PLD2-deficient mice exhibit enhanced IL-6 plasma levels concomitant with enhanced migration of inflammatory cells into the infarct border zone 24 h after acute myocardial infarction." (PMID 33114406, 2020). "This was due to enhanced integrin αIIbβ3 activation of PLD2-deficient platelets under inflammatory conditions, resulting in enhanced IL-6 release of ECs to accelerate inflammation after myocardial infarction, suggesting that PLD2 is an effector of thrombo-inflammation." (PMID 33114406, 2020).
Arterial thrombosis (2 papers, 2016 to 2018). The formation of a blood clot inside an artery. "Deficiency of both PLD isoforms PLD1 and PLD2 as well as pharmacological inhibition of the enzymatic activity of PLD with the PLD inhibitor FIPI protected mice from arterial thrombosis and ischemic brain infarction." (PMID 30555342, 2018).
metastatic cancer (2 papers, 2014 to 2025). A carcinoma which has spread from the original site of growth to another anatomic site. "PLD2 is linked with cancer progression, particularly in metastatic cancers such as triple-negative breast cancer (TNBC), where it enhances cell motility and invasion." (PMID 41223946, 2025). "Small molecules that either indirectly or directly inhibit PLD1 or PLD2 represent novel approaches for the investigation of potential treatment of metastatic cancer." (PMID 24103483, 2014). "Small molecules that directly inhibit PLD1 or PLD2 represent novel approaches for the investigation of potential treatment of metastatic cancer and inflammatory diseases." (PMID 24103483, 2014).
neuroblastoma (2 papers, 2014 to 2025). Neuroblastoma (NB) is the most common solid, extracranial childhood tumor. "The upregulation of PLD2 during ischemia and hypoxia may be involved in the neuroprotective mechanism of ischemic tolerance in the hippocampi of rats, as well as the inhibition of human neuroblastoma cell death induced by chemical hypoxia." (PMID 39796170, 2025).
Obesity (2 papers, 2020 to 2024). Accumulation of substantial excess body fat. "Mice deficient in PLD1 and PLD2 consumed more food and developed obesity, as well as resistance indicating PLD protective role against obesity and its associated metabolic disorders." (PMID 32899471, 2020).
ovarian tumor (2 papers, 2022 to 2024). "We previously reported that both PLD1 and PLD2 are overexpressed in solid metastases and malignant effusions compared with the ovarian tumor in HGSC." (PMID 36362078, 2022). "Since we showed that PLD2 overexpression leads to an increase in CSC-like cells in OC and CSCs were previously proposed to be responsible for chemotherapy resistance and tumor relapse, we wondered whether PLD2 overexpression could cause resistance to conventional therapy in ovarian tumors." (PMID 38403587, 2024).
acute pancreatitis (1 paper, 2023). An acute inflammatory process that leads to necrosis of the pancreatic parenchyma. "Phospholipase D2 targeted by miR‐5132‐5p could attenuate cerulein‐induced acute pancreatitis, specifically by weakening the promoting effect of cerulein on inflammation and apoptosis of AR42J cells." (PMID 37249288, 2023).
brain cancer (1 paper, 2014). A primary or metastatic malignant neoplasm affecting the brain. "A PLD2-specific inhibitor (ML298) and a dual PLD1/PLD2 inhibitor (ML299) were both found to have a potential role in treating brain cancer." (PMID 24103483, 2014).
Cerebral ischemia (1 paper, 2025). Restriction of arterial blood supply to the brain associated with insufficient oxygenation to support the metabolic requirements of the tissue. "Another study found that 3 h after cerebral ischemia, the number of PLD2 mRNA in the brainstem and cerebellum decreased significantly and the inhibition of PLD signal transduction was involved in the induction of apoptosis and necrosis in the cerebellum and brainstem." (PMID 39796170, 2025).
colorectal tumor (1 paper, 2024). "A new study in Spain shows that PLD2, secreted by tumor cells induces senescence in neighbor fibroblasts, increases SASP factors expression and contributes to increased stemness of colorectal tumor cells by activating the Wnt pathway." (PMID 38706911, 2024).
diabetes (1 paper, 2016). "In conclusion, our data suggest that deficiency of PLD1 or PLD2 activity promotes development of overweight and diabetes." (PMID 27299737, 2016).
dyslipidemia (1 paper, 2022). "Phospholipase families of PLD2 and PLD1 were determined as targets for dyslipidemia and can activate MAPK." (PMID 36295794, 2022).
endothelial dysfunction (1 paper, 2025). In vascular diseases, endothelial dysfunction is a systemic pathological state of the endothelium (the inner lining of blood vessels) and can be broadly defined as an imbalance between vasodilating and vasoconstricting substances produced by (or acting on) the endothelium. "AChE and DGKZ directly modulate smooth muscle function, while NLRP3 inflammasome contributes to endothelial dysfunction and smooth muscle cell pyroptosis, and PLD2 is involved in angiotensin generation." (PMID 39981435, 2025).
Erythema (1 paper, 2021). Redness of the skin, caused by hyperemia of the capillaries in the lower layers of the skin. "Macroscopically, the IMQ-induced skin lesions were improved in the PLD2 knockout mice that were topically treated with glycerol and IMQ compared to the IMQ-alone group in terms of erythema, thickening and scaling." (PMID 34445455, 2021).
gastric cancer (1 paper, 2014). A primary or metastatic malignant neoplasm involving the stomach. "PLD2 promotes survival of stomach cancer cells by preventing apoptosis." (PMID 24103483, 2014). "Elevating the levels of PA in the cells was found to enhance the formation of that group, which is necessary for colorectal tumors and are driven by the Wnt/β-catenin pathway and a negative effect on PLD1 and PLD2 expression in AGS and MKN-1 gastric cancer cells." (PMID 24103483, 2014).
Glucose intolerance (1 paper, 2016). Glucose intolerance (GI) can be defined as dysglycemia that comprises both prediabetes and diabetes. "Moreover, increased adiposity and high lipid levels in circulation promote insulin resistance and glucose intolerance in both Pld1-/- and Pld2-/- animals." (PMID 27299737, 2016).
gynecologic cancers (1 paper, 2026). "Common regulatory hubs across gynecologic cancers include hypoxic conditions, cell-cycle regulators such as the DREAM complex, stemness-associated pathways exemplified by the HIF-1α/PLD2 axis, and stromal cell interactions, notably cancer-associated fibroblast-extracellular matrix crosstalk." (PMID 42220495, 2026).
Hepatic steatosis (1 paper, 2016). Steatosis is a term used to denote lipid accumulation within hepatocytes. "Thus, PLD1, but not PLD2, could be related to hepatic steatosis." (PMID 27976696, 2016).
immunodeficiency disorders (1 paper, 2018). "Screening of chemical libraries to activate PLD2 or creation of membrane permeable PA could be a new strategy for the treatment of cancers and immunodeficiency disorders." (PMID 29674728, 2018).
injury (1 paper, 2019). Damage inflicted on the body as the direct or indirect result of an external force, with or without disruption of structural continuity. "Taken together, these results indicate that PLD2 is involved in the intrinsic response pathway of hepatocytes driving the pathogenesis of APAP-induced acute liver injury, and PLD2 may therefore represent an important therapeutic target for patients with drug-induced liver injury." (PMID 31076618, 2019).
invasive breast carcinoma (1 paper, 2017). A carcinoma that infiltrates the breast parenchyma. "Using the Finak Breast dataset from the ONCOMINE cancer microarray database, we determined that PARN was downregulated in invasive breast carcinoma compared to adjacent non-cancerous breast stroma, while gene expression of PLD2 was significantly upregulated in the same dataset." (PMID 28011629, 2017).
ischemia (1 paper, 2020). A hypoperfusion of the BLOOD through an organ or tissue caused by a PATHOLOGIC CONSTRICTION or obstruction of its BLOOD VESSELS, or an absence of BLOOD CIRCULATION. "To investigate if PLD2 has any impact on mycoardial healing and remodeling we ligated the left anterior descending artery (LAD) for 60 min and allowed reperfusion for 24 h after ischemia using PLD2-deficient and wild-type mice." (PMID 32370031, 2020).
lipid metabolism disorder (1 paper, 2022). "The protein–protein interaction was further analyzed, and the targets of PPAP2C, CHPT1, PPAP2B, PLD2 and PLD1 with higher degrees in the PPI network could be the key targets for preventing and treating the lipid metabolism disorder induced by CRE infection." (PMID 36295794, 2022).
memory (1 paper, 2017). The activities involved in the mental information processing system that receives (registers), modifies, stores, and retrieves informational stimuli. "An additional link to AD was provided by detection of enhanced PLD activity in primary neurons after amyloid β application and further corroborated by genetic ablation of PLD2 gene which rescued long-term potentiation (LTP) and memory impairment in an AD mouse model (swAPP)." (PMID 28672041, 2017).
myeloid leukemia (1 paper, 2012). A clonal proliferation of myeloid cells and their precursors in the bone marrow, peripheral blood, and spleen. "Recent study shows that Fes not only binds PA, but to phospholipase D2 (PLD2), leading to increased differentiation of myeloid leukemia cells." (PMID 24957964, 2012).
oral lichen planus (1 paper, 2022). Oral lichen planus is a chronic inflammatory oral condition of unknown aetiology characterized by T-cell-mediated chronic immune response and abnormal epithelial keratinization cycle. "It had been shown that the HIF1α/PLD2 axis was associated with glycolysis and induces T cell immunity in oral lichen planus." (PMID 35256894, 2022).
osteoporosis (1 paper, 2022). A condition of reduced bone mass, with decreased cortical thickness and a decrease in the number and size of the trabeculae of cancellous bone (but normal chemical composition), resulting in increased fracture incidence. "Therefore, the modulation of PLD2 may provide a novel strategy for treating skeletal diseases, including osteoporosis and rheumatoid arthritis." (PMID 35945449, 2022).
ovarian carcinoma (1 paper, 2024). A malignant neoplasm originating from the surface ovarian epithelium. "Here we find that PLD2 is also overexpressed in ovarian cancer patients, being associated with poor patient survival." (PMID 38403587, 2024). "Here, we show that hypoxia induces CSC formation and chemoresistance in ovarian cancer through transcriptional activation of the PLD2 gene." (PMID 38403587, 2024). "Importantly, hypoxia-induced stemness is dependent on PLD2 expression, demonstrating that PLD2 is a major determinant of de-differentiation of ovarian cancer cells to stem-like cells in hypoxic conditions." (PMID 38403587, 2024).
papillary thyroid cancer (1 paper, 2008). "In human papillary thyroid cancer, the expression levels of PLD2 protein were higher than those in the corresponding paired normal tissues." (PMID 18498667, 2008).
sarcoma (1 paper, 2010). A usually aggressive malignant neoplasm of the soft tissue or bone. "Ewing's sarcoma fusion protein, EWS/Fli, has been reported to induce selective PLD2 expression by binding to the ETS domain of the PLD2 promoter." (PMID 20711340, 2010).
schizophrenia (1 paper, 2021). A major psychotic disorder characterized by abnormalities in the perception or expression of reality. "We noticed four of the DEGs (PLD2, PLCB3, PLAAT4, RPS27) involved in these pathways were also differentially expressed in the brain of patients with schizophrenia." (PMID 34630179, 2021).
status epilepticus (1 paper, 2019). Status epilepticus is defined as a continuous seizure lasting more than 30 min, or two or more seizures without full recovery of consciousness between any of them. "Changes to Pld2 have been reported after status epilepticus within reactive astrocytes and also DG granule neurons." (PMID 32009885, 2019).
Stroke (1 paper, 2020). Sudden impairment of blood flow to a part of the brain due to occlusion or rupture of an artery to the brain. "These tests also revealed that the inhibition of either PLD1 or both PLD1 and PLD2 affords protective effects against neurological deficit after stroke." (PMID 32971863, 2020).
thrombosis (1 paper, 2025). "Moreover, direct comparison of PLD1 and PLD2 in the same thrombosis model will be important to clarify isoform specificity and potential redundancy." (PMID 41194921, 2025).
thymoma (1 paper, 2010). A neoplasm arising from the epithelial cells of the thymus. "Previous studies from our lab have shown that overexpression of catalytically active PLD2 in EL4 thymoma cells lacking PLD2 results in increased spreading and elongation of transfected cells, while inactive PLD2 produces the opposite effect." (PMID 27713341, 2010).
thyroid cancer (1 paper, 2014). "A transmodulation between PLD2 and the oncogenic kinase RET is evident in thyroid cancer cells where PLD2 enhances STAT3 phosphorylation and transcriptional activation that is mediated by RET." (PMID 24103483, 2014).
triple-negative breast carcinoma (1 paper, 2025). An invasive breast carcinoma which is negative for expression of estrogen receptor (ER), progesterone receptor (PR), and human epidermal growth factor receptor 2 (HER2). "Oleate (OA) has been shown to activate PLD2 and promote triple-negative breast cancer (TNBC) cell migration, but the underlying molecular mechanisms remain poorly understood." (PMID 41223946, 2025).